LINC00691 (long independently transcribed non-coding RNA 691)
Gene: Long non-coding RNA gene on chromosome 3 (24,096,269 to 24,103,238, reverse strand). Ensembl gene ENSG00000224074.
Diseases named in the same sentence as LINC00691 in open-access papers:
LINC00691 is named in the same sentence as 10 diseases in open-access papers, as found by Europe PMC text mining. Sharing a sentence is not in itself a finding about the gene and the disease. The quoted sentences say what the papers report.
gastric cancer (3 papers, 2022 to 2023). A primary or metastatic malignant neoplasm involving the stomach. "LINC00691 has also been confirmed to be highly expressed in gastric cancer patients, which simultaneously promotes the expression of epithelial growth factor to accelerate the proliferation and invasion of gastric cancer cells." (PMID 35361740, 2022). "A previous study has shown that LINC00691 overexpression promotes invasion and proliferation in gastric cancer cells." (PMID 35256924, 2022).
non-small cell lung carcinoma (2 papers, 2022 to 2023). A group of at least three distinct histological types of lung cancer, including non-small cell squamous cell carcinoma, adenocarcinoma, and large cell carcinoma. "RT-qPCR detection and survival analysis from more than 100 clinical samples reveal that the expression of LINC00691 is also up-regulated in non-small cell lung cancer, which is associated with poor prognosis." (PMID 35361740, 2022). "Other related studies reported that LINC00691 was abnormally expressed in non-small cell lung cancer, lung adenocarcinoma, osteosarcoma, and papillary thyroid cancer." (PMID 37784036, 2023).
lymph node metastasis (1 paper, 2023). "In the previous study, we reported that overexpressed LINC00691 in GC tissues and serum was a potential biomarker for GC, which was correlated with tumor size, depth of invasion, lymph node metastasis, venous invasion, perineural invasion, and poor prognosis of patients." (PMID 37784036, 2023).
renal cell carcinoma (1 paper, 2022). "Upregulation of LINC00691 is also found in renal cell carcinoma." (PMID 35361740, 2022).
tumor (2 papers, 2023 to 2025). "In our previous study, we found that LINC00691 level was associated with tumor size, lymph node metastasis, invasion depth, and prognosis of patients." (PMID 37784036, 2023).
cancer (1 paper, 2022). A tumor composed of atypical neoplastic, often pleomorphic cells that invade other tissues. "The distinct LINC00691 functions in various cancer cells may be associated with their specific characteristics." (PMID 35256924, 2022).
LINC00691 also shares sentences with these, for which no sentence is quoted: lung adenocarcinoma (1 paper); melanoma (1); osteosarcoma (1); papillary thyroid cancer (1).